SLC25A17 (solute carrier family 25 member 17)
Description:
Peroxisomal transporter for multiple cofactors like coenzyme A (CoA), flavin adenine dinucleotide (FAD), flavin mononucleotide (FMN) and nucleotide adenosine monophosphate (AMP), and to a lesser extent for nicotinamide adenine dinucleotide (NAD(+)), adenosine diphosphate (ADP) and adenosine 3',5'-diphosphate (PAP). May catalyze the transport of free CoA, FAD and NAD(+) from the cytosol into the peroxisomal matrix by a counter-exchange mechanism.
Synonyms: PMP34
Tractability: Antibody: UniProt predicts a signal peptide or a membrane-spanning region. PROTAC: ubiquitination databases record sites on it; its protein half-life has been measured.
Gene: Protein-coding gene on chromosome 22 (40,769,630 to 40,819,401, reverse strand). Ensembl gene ENSG00000100372.
Subcellular location: Cytoplasm; Peroxisome membrane
Subcellular location (Human Protein Atlas): Peroxisomes
Pathways (Reactome):
Metabolism: Alpha-oxidation of phytanate
Protein localization: Class I peroxisomal membrane protein import
Gene Ontology:
Molecular function: ADP transmembrane transporter activity; AMP transmembrane transporter activity; ATP transmembrane transporter activity; coenzyme A transmembrane transporter activity; FAD transmembrane transporter activity; FMN transmembrane transporter activity; NAD transmembrane transporter activity; protein binding; protein-folding chaperone binding; adenine nucleotide transmembrane transporter activity
Biological process: ATP transport; fatty acid beta-oxidation; fatty acid transport; nucleotide transmembrane transport; fatty acid alpha-oxidation; ADP transport; AMP transport; coenzyme A transmembrane transport; FAD transmembrane transport; NAD transmembrane transport; transmembrane transport
Cellular component: cytoplasm; membrane; peroxisomal membrane; peroxisome; cytosol
Genetic constraint (gnomAD): Loss-of-function variants: 17 observed, 28.35 expected, observed/expected ratio (o/e) 0.6, 90% interval 0.41 to 0.9. The upper end of that interval is the gene's LOEUF score, 0.9, which puts it in group 3 of 6, group 1 being the genes least tolerant of losing a copy. Missense variants: 272 observed, 321.67 expected, observed/expected ratio (o/e) 0.85, 90% interval 0.76 to 0.94. Synonymous variants: 113 observed, 124.64 expected, observed/expected ratio (o/e) 0.91, 90% interval 0.78 to 1.06.
Homologues: Orthologues: chimpanzee SLC25A17 (99% identical), macaque SLC25A17 (98% identical), dog SLC25A17 (97% identical), rabbit SLC25A17 (96% identical), mouse Slc25a17 (95% identical), guinea pig SLC25A17 (95% identical), rat Slc25a17 (94% identical), pig SLC25A17 (80% identical), zebrafish slc25a17 (58% identical). Paralogues in human: SLC25A13 (24% identical), SLC25A12 (24% identical), SLC25A19 (24% identical), SLC25A21 (24% identical), SLC25A16 (23% identical), SLC25A42 (23% identical), SLC25A39 (22% identical), SLC25A24 (22% identical), SLC25A28 (22% identical), SLC25A29 (21% identical), SLC25A32 (21% identical), SLC25A48 (21% identical), and 37 more.
Diseases named in the same sentence as SLC25A17 in open-access papers:
SLC25A17 is named in the same sentence as 13 diseases in open-access papers, as found by Europe PMC text mining. Sharing a sentence is not in itself a finding about the gene and the disease. The quoted sentences say what the papers report.
prostate carcinoma (5 papers, 2023 to 2024). A carcinoma that arises from epithelial cells of the prostate gland. "Clinical analysis of prostate cancer specimens indicated patient with high SLC25A17 expression had a worse prognosis compared to those with low SLC25A17 expression." (PMID 38402166, 2024). "In enzalutamide-resistant prostate cancer cells, suppression of SLC25A17 led to delayed cell cycle progression and reduced protein expression of Cyclin D1 and CDK6." (PMID 38402166, 2024). "Previous studies confirmed that EPHX2, RXRA, LTC4S and SLC25A17 were abnormally expressed in prostate cancer tissues and affected the malignant biological behaviour of prostate cancer cells and prognosis of patients." (PMID 36643625, 2023). "Another report shows that SLC25A17 plays an essential role in the development of enzalutamide resistance which is used for the treatment of advanced-stage prostate cancer, and SLC25A17 may be identified as a therapeutic target to circumvent drug resistance." (PMID 37386359, 2023). "A current study in prostate cancer proposed that the abnormal expression of SLC12A5, SLC25A17, and SLC27A6 were strong to metabolic reprogramming and the development of resistance against chemotherapeutic drugs." (PMID 38136890, 2023).
neuroblastoma (2 papers, 2015 to 2020). Neuroblastoma (NB) is the most common solid, extracranial childhood tumor. "However, only one relevant study reported its role in tumors, showing that genetic changes in SLC25A17 (CNV deletion) were closely associated with the overall survival rate and relapse-free survival rate of neuroblastoma patients." (PMID 33552118, 2020).
adrenomyeloneuropathy (1 paper, 2018). An adult form of the peroxisomal disease X-linked adrenoleukodystrophy (X-ALD), characterized by spastic paraparesia and often associated with peripheral adrenal insufficiency in males. "The SLC25A17 gene is also involved in adrenomyeloneuropathy, an inherited condition in which long chain fatty acids accumulate in the central nervous system (CNS) disrupting several brain functions." (PMID 30120083, 2018).
breast carcinoma (1 paper, 2024). "SLC25A17 was highly expressed in breast cancer tissues, which was found to be associated with unfavorable prognosis." (PMID 38402166, 2024). "In the current study, bioinformatical analysis revealed significant up-regulation of SLC25A17 in breast cancer tissues, correlating with poor prognosis." (PMID 38402166, 2024). "Additionally, analysis of TCGA, GSE45827 and GSE29044 datasets revealed a significant increase in SLC25A17 expression in breast cancer tissues." (PMID 38402166, 2024). "In the current study, we have made an important discovery by demonstrating that SLC25A17 is upregulated in breast cancer tissues compared to adjacent tissues, which has not been reported previously." (PMID 38402166, 2024).
breast tumor (1 paper, 2024). "In a nude mice xenograft study, SLC25A17 knockdown markedly decreased breast tumor growth and metastasis." (PMID 38402166, 2024).
head and neck squamous cell carcinoma (1 paper, 2023). A squamous cell carcinoma that arises from any of the following anatomic sites: lip and oral cavity, nasal cavity, paranasal sinuses, pharynx, larynx, and salivary glands. "This study aims to explore the predictive value of SLC25A17 in the prognosis and tumor microenvironment (TME) of patients with head and neck squamous cell carcinoma (HNSCC) and to provide ideas for individual clinical treatment." (PMID 37386359, 2023). "SLC25A17 may play a role in the tumorigenesis, development and efficacy of cancer; however, the application value of SLC25A17 as a biomarker in head and neck squamous cell carcinoma has not been explored." (PMID 37386359, 2023).
lymph node metastasis (1 paper, 2023). "Univariate Cox and multivariate COX analyses showed that SLC25A17, age, and lymph node metastasis are independent prognostic risk factors for HNSCC, and the survival prediction model based on these factors had reliable predictive value." (PMID 37386359, 2023). "The expression level of SLC25A17, age, and lymph node metastasis were three independent risk factors, in which the SLC25A17 expression level had the highest risk ratio." (PMID 37386359, 2023). "It shows that different SLC25A17 expression, age, and lymph node metastasis have a corresponding score, and the total score they add up corresponds to the 1-, 3-, and 5-year survival rates of HNSCC patients below." (PMID 37386359, 2023). "Univariate COX and multivariate COX analyses were performed for SLC25A17 expression level, age, gender, grade, stage, T stage and lymph node metastasis." (PMID 37386359, 2023). "The survival prediction nomogram based on SLC25A17 expression, age and lymph node metastasis from GSE65858 was constructed, and it also shows that there is a certain consistency between the actual observations and nomogram predictions." (PMID 37386359, 2023). "Notably, the survival nomogram based on SLC25A17, age, and lymph node metastasis could better predict the prognosis of patients with HNSCC." (PMID 37386359, 2023). "The results showed that the P values of SLC25A17 expression level (HR uni-Cox: 1.602, HR multi-Cox: 1.520), age (HR uni-Cox: 1.020, HR multi-Cox: 1.024) and lymph node metastasis (HR uni-Cox: 1.553, HR multi-Cox: 1.374) were all less than 0.05 and could be used as independent prognostic factors." (PMID 37386359, 2023). "The clinical information of the SLC25A17 high- and low-expression groups in the TCGA-HNSC cohort was compared, including age, gender, grade, stage, T stage, and lymph node metastasis." (PMID 37386359, 2023).
cancer (4 papers, 2015 to 2024). A tumor composed of atypical neoplastic, often pleomorphic cells that invade other tissues. "Data showed that SLC25A17 is expressed in malignant tumor cells, immune cells, and stromal cells (such as endothelial cells, myofibroblasts, etc.)but not in muscle cells." (PMID 37386359, 2023). "In the TCGA-HNSC cohort of 504 tumor tissues and 44 normal para-carcinoma tissues, the expression of SLC25A17 in tumor tissues was significantly higher than that in normal para-carcinoma tissues, and IHC slides from THPA also supported the result." (PMID 37386359, 2023). "Additionally, SLC25A17 exhibited elevated expression in HNSCC tissues compared to normal para-carcinoma tissues, correlating with poorer survival outcomes in patients with high SLC25A17 expression." (PMID 38402166, 2024). "SLC25A17 may also play a role in the tumorigenesis, development and efficacy of cancer." (PMID 37386359, 2023). "Our data showed that SLC25A17 was expressed in malignant tumor cells, immune cells and stromal cells but not in myocytes, and this difference might be caused by the small number of muscle cells in the sample tissue." (PMID 37386359, 2023).
tumor (3 papers, 2020 to 2024). "SLC25A17 mRNA expression levels were significantly upregulated in tumor tissues compared to normal tissues." (PMID 38402166, 2024). "Tumor tissues with low SLC25A17 expression showed more significant infiltration of CD8+ T cells, regulatory T cells, and PMNs." (PMID 37386359, 2023). "This study showed that the expression level of SLC25A17 in HNSCC tumor samples was higher than that in normal tissues." (PMID 37386359, 2023). "Furthermore, our study provided the first evidence that knockdown of SLC25A17 inhibited tumor cell growth by inducing ROS-mediated autophagy." (PMID 38402166, 2024). "Several studies have reported the involvement of SLC25A17 in tumor progression." (PMID 38402166, 2024). "SLC25A17 may promote tumor cell growth by regulating the neural active ligand receptor interaction signaling pathway." (PMID 37386359, 2023). "Compared with normal samples, the expression of SLC25A17 was much higher in HNSCC tumor samples." (PMID 37386359, 2023).
SLC25A17 also shares sentences with these, for which no sentence is quoted: autoimmune thyroid disease (1 paper); prostate adenocarcinoma (1); Refsum disease (1); triple-negative breast carcinoma (1).